MSTN (myostatin)
Diseases named in the same sentence as MSTN in open-access papers (continued):
Sharing a sentence is not in itself a finding about the gene and the disease.
Atrophy (30 papers, 2014 to 2026). Any weakening or degeneration, especially through lack of use. "Therefore, we posit that MSTN-induced atrophy observed in the current study is likely linked to the MSTN-induced down-regulation in Akirin-1/Mighty mRNA." (PMID 25132809, 2014). "Dexamethasone-induced muscle atrophy results from elevated muscle protein degradation and reduced synthesis, as evidenced by the upregulation of myostatin promoter activity." (PMID 38201986, 2024). "Many diseases are characterized by muscle atrophy and inhibition of myostatin has emerged as an appealing therapeutic approach that alleviates overall muscle weakness and enhances the performance of daily activities, thus improving quality of life." (PMID 37894805, 2023). "Muscle atrophy induced by the TGF-β member myostatin involves Smad2/3 signaling that activates MAFbx expression and downregulates mTOR signaling." (PMID 36402791, 2022). "An increased expression of myocardial atrophy factors atrogin-1 and myostatin was observed by Dox administration, and these increased expressions were suppressed by the administration of HSA-Trx." (PMID 35335938, 2022). "Becker muscular dystrophy, inclusion body myositis, and facioscapulohumeral muscular dystrophy patients with less prominent muscle atrophy show higher circulating myostatin concentrations than DMD and SMA patients but lower levels than normal controls." (PMID 36012334, 2022). "In many muscle atrophy models, both MAFbx (Atrogin-1), a gene related to muscle atrophy, and myostatin (a suppressor of muscle growth) have increased simultaneously." (PMID 29385720, 2018). "Here we show that the expression of components of the myostatin signaling pathway is downregulated in muscle wasting or atrophying diseases, with a decrease of myostatin and activin receptor, and an increase of the myostatin antagonist, follistatin." (PMID 29192144, 2017). "Muscle atrophy follows known pathways via both myostatin signaling and expression of muscle-specific ubiquitin ligases, atrogin-1 and MuRF1." (PMID 29312148, 2017). "In summary, our data provides further support for the notion that specific antagonism of myostatin can enhance skeletal muscle mass and function in normal mice and multiple settings of atrophy." (PMID 26457176, 2015). "Treatment significantly reduces MSTN protein levels in skeletal muscle, promotes muscle mass gain in healthy mice, and protectes skeletal muscles from atrophy in cancer- and dexamethasone-induced muscle atrophy models." (PMID 41041909, 2025). "We demonstrated the protective effect of QGs in DEX-induced muscle atrophy, which might depend on the suppression of myostatin signaling." (PMID 30805562, 2019). "For example, situations where atrophy is a prevalent symptom may display higher, lower or comparable expression of myostatin in circulation." (PMID 32652899, 2020). "Furthermore, our data suggests that myostatin might be a therapy to administer during unloading-induced atrophy to protect the fast-twitch fibres in particular - a view that is perhaps contentious and departs from current dogma." (PMID 24718581, 2014). "Pharmacological intervention to inhibit the myostatin pathway is therefore considered an attractive therapeutic approach for various types of muscle disorders, such as muscular dystrophy and atrophy, for which no effective treatment is currently available." (PMID 33495503, 2021). "Overproduction of myostatin and activins, inflammatory responses, and impaired insulin-like growth factor 1 (IGF-1)-dependent protein synthesis are known to be closely related to the pathogenesis of muscle atrophy." (PMID 32244785, 2020). "The knowledge that myostatin inhibition is not a ubiquitous treatment option for all forms of atrophy will aid in providing targeted therapies to individual patients." (PMID 24504412, 2014).
Atrophy (continued). "Although they have shown that their antibody has the capacity to increase muscle mass in vivo using a steroid-mediated atrophy mouse model, they did not compare the effects of their antibody with those of anti-mature myostatin antibodies that have GDF11 cross-reactivity." (PMID 33495503, 2021).
Cirrhosis (28 papers, 2019 to 2025). A chronic disorder of the liver in which liver tissue becomes scarred and is partially replaced by regenerative nodules and fibrotic tissue resulting in loss of liver function. "Serum zinc levels are often low in cirrhosis, and serum zinc levels and myostatin levels show an inverse correlation." (PMID 38256036, 2024). "By contrast, we found that myostatin levels were lower among patients, despite the severe liver failure observed in some of the included patients with cirrhosis, six of whom developed chronic encephalopathy." (PMID 36769301, 2023). "In this study we show that myostatin levels are decreased in patients with cirrhosis, with lower levels in patients with acute decompensation and acute-on chronic liver failure (ACLF)." (PMID 37554924, 2023). "Low myostatin levels in cirrhosis predict the development of ACLF and mortality independently of liver disease severity and sex." (PMID 37554924, 2023). "This provides more information regarding myostatin levels during the crucial events in the natural history of cirrhosis." (PMID 37554924, 2023). "Further studies are required to disentangle the connections between the proinflammatory state of alcoholics, especially if cirrhosis ensues, the altered fat deposition and muscle atrophy of these patients, and the altered myostatin levels." (PMID 36769301, 2023). "Patients with cirrhosis have higher circulating myostatin levels compared with the control subjects." (PMID 34070910, 2021). "However, it was also shown that there is a progressive decrease in myostatin levels as cirrhosis progresses." (PMID 39971588, 2025). "Another limitation of our study is that we were unfortunately unable to analyze serum for biomarkers of intestinal permeability, bacterial translocation, myostatin, ammonia, bile acids, and others that are thought to be involved in the gut-muscle axis in cirrhosis." (PMID 39539377, 2024). "Myostatin is a cytokine belonging to the transforming growth factor beta 1 family and a negative regulator of muscle hypertrophy; its quantity increases in patients with cirrhosis, thereby inhibiting skeletal myogenesis." (PMID 38530830, 2024). "In cirrhosis, this inhibitory effect of follistatin on myostatin is reduced." (PMID 37554924, 2023). "Therefore, this study aimed to evaluate the association of myostatin levels with the development of ACLF and mortality in patients with cirrhosis." (PMID 37554924, 2023). "In addition, in patients with cirrhosis, significantly elevated levels of ammonia can increase myostatin expression." (PMID 38255652, 2023). "This study describes the association of myostatin with ACLF development; the manuscript aimed to provide evidence that muscle impairment, as indicated by myostatin levels, is associated with increased severity of cirrhosis, ACLF, and survival." (PMID 37554924, 2023). "However, when performing a logistic regression analysis comparing OSA fat with age, myostatin (both as dichotomic variables according to median values) and cirrhosis, myostatin was displaced by age, which remained as the sole variable related to OSA fat." (PMID 36769301, 2023). "Ammonia levels in skeletal muscle are substantially elevated in patients with cirrhosis, thus resulting in the induction of the transcription factor NF-κB and a further increase in the myostatin expression, followed by the inhibition of myogenesis and an increase in autophagy." (PMID 33803020, 2021). "Particularly, in patients with NASH-related cirrhosis, there were no data regarding the association between serum myostatin and clinical outcomes." (PMID 33198216, 2020). "In our study of 198 patients with cirrhosis, for the entire cohort, the 1-, 3-, and 5-year cumulative overall survival (OS) rates were 93.9%, 72.7%, and 50.4%, respectively, in the higher myostatin group, and 97.0%, 83.3%, and 73.6%, respectively, in the lower myostatin group (p = 0.0001)." (PMID 39940810, 2025).
Cirrhosis (continued). "In cirrhosis, myostatin levels are decreased in patients with acute decompensation and acute-on-chronic liver failure (ACLF), and low serum myostatin independently predicts ACLF development and mortality, irrespective of liver disease severity or sex." (PMID 41515940, 2025). "This study showed the prognostic performance of serum myostatin for HCC development and also validated the influence of serum myostatin levels on survival in a previous study in a large cohort of patients with cirrhosis." (PMID 33198216, 2020). "Multiple intracellular signaling pathways such as the IGF1/AKT, myostatin, cytokine/NFκB, and AMPK pathways interact and regulate muscle mass and protein metabolism, which are disrupted in cirrhosis." (PMID 31392488, 2019). "Skeletal muscle of mice with cirrhosis induced by bile duct ligation (BDL) had myasthenia and a significant decrease in the expression levels of Akt and mTOR, while the expression of myostatin, which negatively regulated the activity of the Akt–mTOR axis, was increased." (PMID 37881635, 2023). "In all these cases, the relationships between myostatin and fat variables were independent of age or the presence or not of cirrhosis, as assessed by stepwise multiple regression analyses." (PMID 36769301, 2023). "Therefore, if inflammation downregulates myostatin production, it is expected that as inflammation increases in the progression of compensated cirrhosis to AD and ACLF, myostatin levels would decrease." (PMID 37554924, 2023). "There is published data showing increased levels of myostatin, a negative muscle growth regulator, in the muscle of patients with compensated cirrhosis." (PMID 31590379, 2019). "Previous studies showed that serum myostatin also had good prognostic performance of survival and HCC development in a population of whom 58.6% had predominantly hepatitis C virus (HCV)-related liver cirrhosis and 39.4% had hepatitis B virus (HBV)-related cirrhosis." (PMID 33198216, 2020). "Therefore, it is not surprising that myostatin levels in alcoholics with cirrhosis may differ from those observed in alcoholics without cirrhosis." (PMID 36769301, 2023).
cardiac hypertrophy (24 papers, 2010 to 2025). "Adult male and female MSTN-null mice have larger hearts than wild-type mice, indicating that MSTN deficiency results in eccentric cardiac hypertrophy." (PMID 41011274, 2025). "MSTN deletion in adult mouse cardiomyocytes causes cardiac hypertrophy and dysfunction." (PMID 41011274, 2025). "This is interesting, given that previous research has also described how variation in the delicate balance between follistatin/myostatin activity likely facilitates cardiac hypertrophy." (PMID 41132156, 2025). "Despite this, most data show that removal of myostatin results in myocardial hypertrophy, whereas its overexpression reduces the heart mass." (PMID 38136649, 2023). "Because follistatin is an inhibitor of myostatin, such a shift in follistatin/myostatin balance would facilitate the heart hypertrophy in the course of training." (PMID 38136649, 2023). "MiR-208a and miR-208b are expressed in both the left atrium and left ventricle, and they share a similar sequence that allows them both to regulate myocardial hypertrophy by targeting Thrap1 and myostatin." (PMID 35717150, 2022). "MSTN has a vital function in the heart, as demonstrated by a previous study, in maintaining cardiac energy homeostasis and the preventing of ventricular hypertrophy." (PMID 35780124, 2022). "This study was conducted to precisely resolve the relationships among GDF11, myostatin, and cardiac hypertrophy, while simultaneously comparing their genetic architectures to uncover any mechanisms that link them." (PMID 34510201, 2021). "This study was conducted to resolve the statistical and genetic relationships among GDF11, myostatin, and cardiac hypertrophy in a mouse model of human genetics, the Diversity Outbred (DO) stock." (PMID 34510201, 2021). "The effects of these phenomena can be observed in the case of myostatin-related muscle hypertrophy or cardiac hypertrophy." (PMID 32366041, 2020). "Blocking myostatin signaling in the heart by genetically inactivating myostatin from cardiomyocytes results in enhanced glycolysis, augmented glycogen storage, and cardiac hypertrophy in adult mice." (PMID 30765322, 2019). "Larger increases were seen in limb muscles than in the heart, a result consistent with previous investigations of cardiac hypertrophy with myostatin blockade." (PMID 30368252, 2018). "A possible mechanism for the observed cardiac hypertrophy is reduced myostatin signaling through the activin IIB receptor which is expressed at similar levels in the heart compared to skeletal muscle." (PMID 20161803, 2010). "Such an elevation in the myocardial level of myostatin could exert a direct inhibitory effect on development of heart hypertrophy during training." (PMID 38136649, 2023). "Changed heart muscle mass in hypertrophy or chronic heart failure creates new conditions for mechanical work, and could result in increased production of myostatin." (PMID 38136649, 2023). "Overall, we discovered unique relationships among GDF11, myostatin, and indicators of cardiac hypertrophy, as well as distinct loci and candidate genes behind each phenotype, and our results point to molecular pathways that will be interrogated in future studies of GDF11 and the heart." (PMID 34510201, 2021). "Myostatin modulation in skeletal muscles with DCA-conjugated siRNAs rescues muscle loss, but unwanted accumulation and silencing in cardiac muscles could result in cardiac hypertrophy." (PMID 38348876, 2024). "However, MSTN regulates autophagy differently in cells with myocardial hypertrophy." (PMID 37288303, 2023). "In dystrophin-deficient animals, MSTN germ-line inactivation does not promote cardiac hypertrophy or reduce cardiac fibrosis, showing that MSTN does not operate in heart muscle as it does in skeletal muscle, demonstrating the significance of endogenous MSTN for adult cardiomyocyte metabolism." (PMID 35780124, 2022).
cardiac hypertrophy (continued). "In addition, deficiency of myostatin does not induce ventricular hypertrophy, compared with wild-type mice." (PMID 35155444, 2021). "However, long-term (11 months) myostatin inhibition using a recombinant AAV to overexpress myostatin propeptide in mdx mice did not reduce the amount of fibrosis in the diaphragm, but caused cardiac hypertrophy and impaired function in a dose-dependent manner." (PMID 21798096, 2011). "The interaction between MDM2 and TCAP is known to be important for cardiac hypertrophy, it was also shown that TCAP controls secretion of MSTN." (PMID 32928103, 2020). "This would suggest that myostatin is a negative feedback regulator of angiotensin II-induced heart hypertrophy." (PMID 38136649, 2023). "There are data indicating that removal of myostatin does not result in heart hypertrophy or affect cardiomyocyte size." (PMID 38136649, 2023). "In a recent study using a mouse model of AS, treatment with monoclonal anti-myostatin antibodies failed to reduce cardiac hypertrophy or fibrosis." (PMID 37958492, 2023). "Though myostatin has an established, anti-hypertrophic effect on muscle, including a direct regulatory effect on cardiomyocytes, it still remains unclear whether GDF11 has the same, or distinct, effects on cardiac hypertrophy." (PMID 34510201, 2021). "First, it was supposed that elevated plasma myostatin might come out of the myocardium in COPD patients who had RV dysfunction and/or hypertrophy, but heart biopsy was not performed in the patients." (PMID 26998756, 2016). "There is an over-activated autophagy level in myocardial cells during myocardial hypertrophy, while in mice lacking MSTN, abdominal aortic coarctation (AAC) was aggravated and accompanied by an increase in angiotensin II-induced autophagy, which was reversed in vivo and in vitro by MSTN treatment." (PMID 37288303, 2023).
metabolic syndrome (24 papers, 2013 to 2025). A cluster of metabolic risk factors for CARDIOVASCULAR DISEASES and TYPE 2 DIABETES MELLITUS. "In obese patients, myostatin was related to insulin resistance, proinflammatory cytokines, and the presence of three or more criteria of the metabolic syndrome." (PMID 36769301, 2023). "In this review, we describe the transcriptional regulation and receptor binding pathway of MSTN, then introduce the role of MSTN in regulating mitochondrial function and autophagy, review the research progress of MSTN in metabolic syndrome." (PMID 37288303, 2023). "MSTN have also been reported to be involved in another important clinical manifestation of metabolic syndrome: hypertension." (PMID 37288303, 2023). "Lower serum MSTN levels were also observed in people with metabolic syndrome, central obesity, and higher TG and lower HDL-C levels." (PMID 35330038, 2022). "The same study found that myostatin levels are correlated with the number of metabolic syndrome criteria met, insulin levels and insulin sensitivity." (PMID 32796600, 2020). "We have observed that a lower serum myostatin concentration is related to metabolic syndrome, central obesity, low high-density lipoprotein cholesterol, and high TG among 246 diabetic patients after adjusting age and gender." (PMID 28077934, 2017). "Finally summarize some MSTN inhibitors under clinical trial and proposed the use of MSTN inhibitor as a potential target for the treatment of metabolic syndrome." (PMID 37288303, 2023). "However, the evidence about the influence of myostatin on insulin action and IR seems contradictory: Plasma myostatin decreases with increasing number of metabolic syndrome criteria in human patients." (PMID 29445355, 2018). "Thus, inhibition of Myostatin increases the osteogenic potential and bone mineralization, and reduces the impact of the metabolic syndrome." (PMID 28852138, 2017). "A study on healthy, obese and metabolically unhealthy participants found a contradictory, significantly negative correlation between muscle mass and serum myostatin, suggesting a major influence of metabolic syndrome on circulating myostatin level." (PMID 32796600, 2020). "Also against a direct involvement of myostatin in human IR, a study of 246 subjects found people with more severe metabolic syndrome to have lower, not higher plasma myostatin." (PMID 29445355, 2018). "The over-expression of myostatin in ZF4-SC by ZFS, but also a lower but significant one by ZLS (absent in ZL4-SC), and the role of dyslipidemia in this process needs to be clarified in future studies vis-à-vis quantitative determinations of lipid factors in both types of serum." (PMID 31430893, 2019).